VWF (von Willebrand factor)
Diseases named in the same sentence as VWF in open-access papers (continued):
Sharing a sentence is not in itself a finding about the gene and the disease.
thrombotic microangiopathy (69 papers, 2012 to 2026). The syndromes of microangiopathic hemolytic anemia, thrombocytopenia, and variable signs of organ impairment, due to platelet aggregation in the microcirculation. "The correlation between primary biological markers and differences in patient progress between therapeutic groups supports a likely causal effect of antagonizing the vWF–GPIb interaction on the rapid resolution of thrombotic microangiopathy." (PMID 41303245, 2025). "The detection of ADAMTS13 deficiency remains essential for identifying thrombotic microangiopathies that produce life-threatening blood clots through impaired VWF cleavage." (PMID 40725629, 2025). "TTP is a rare thrombotic microangiopathy, caused by the deficiency of a specific protease targeting the von Willebrand factor, called ADAMTS13." (PMID 37830631, 2023). "Severe ADAMTS13 deficiency results in reduced VWF cleavage and the accumulation of UL-VWF multimers, which promote the formation of platelet-rich thrombi in arterioles and capillaries that trigger a thrombotic microangiopathy." (PMID 35327035, 2022). "ADAMTS13 is the main VWF-cleaving protease and its deficiency results in development of thrombotic microangiopathy." (PMID 28139439, 2017). "SARS-CoV-2 thereby increases the risk of thrombotic microangiopathy by potentially two synergistic mechanisms: First, the ubiquitous endothelial damage induces an excessive release of VWF, exceeding the protease activity of physiological concentrations of ADAMTS13." (PMID 37380654, 2023). "However, only in the presence of severe ADAMTS-13 deficiency (level<6%), ultra-large VWF multimers accumulate, causing thrombotic microangiopathies." (PMID 23383177, 2013). "This proteolytic cleavage is essential to reduce the size of ultra-large VWF polymers, which, when exposed to high shear stress in the microcirculation, are prone to form with platelets clumps, which cause severe syndromes called thrombotic microangiopathies (TMAs)." (PMID 24106608, 2013). "Research has shown that NETs can bind to vascular endothelial cells via von Willebrand factor (vWF) and P-selectin, providing a scaffold for platelet aggregation, which leads to fibrin deposition and thrombotic microangiopathy." (PMID 41221274, 2025). "TTP is a rare but life-threatening thrombotic microangiopathy caused by a severe deficiency in ADAMTS13, a metalloprotease responsible for cleaving ultra-large von Willebrand factor (vWF) multimers." (PMID 40827194, 2025). "ADAMTS13, a metalloprotease responsible for cleaving ultra-large von Willebrand factor (vWF) multimers, plays a crucial role in regulating platelet aggregation and preventing thrombotic microangiopathy." (PMID 40868959, 2025). "There are particularities of cocaine intoxication pathophysiology that can trigger thrombotic microangiopathies because of vasoconstriction, direct endothelial injury, platelet activation, and increasing von Willebrand factor and fibrinogen levels." (PMID 37646745, 2023). "The presence of (at least localized) thrombotic microangiopathy is supported by observations of abnormal von Willebrand factor/ADAMTS-13 ratios." (PMID 33368021, 2021). "In related work, microvascular occlusion due to thrombotic microangiopathy has been proposed as a molecular mechanism for hepatic fibrosis, with increased synthesis of von Willebrand factor (vWF) by endothelial cells or hepatocytes playing a vital role." (PMID 34202091, 2021). "Since the activation of ADAMTS13 was reduced remarkably, the thrombotic tendency was determined to be a thrombotic microangiopathy-like condition owing to increased vWF." (PMID 34090366, 2021). "Disturbances in the glycocalyx and von Willebrand factor clearly can facilitate hypertensive emergency complications like thrombotic microangiopathy." (PMID 33644125, 2020).
thrombotic microangiopathy (continued). "The complexity of coagulation, involving intricate interactions between various factors, is further complicated in the xenotransplantation context, particularly by abnormal pig vWF interactions, inefficient pig thrombomodulin, thrombotic microangiopathy, and consumptive coagulopathy." (PMID 39404060, 2025). "ECs perturbation, increased release of vWF, and relatively insufficient vWF cleavage owing to the deficiency of ADAMTS13 are responsible for increased interactions between platelets and the vessel wall to cause thrombotic microangiopathies." (PMID 36466841, 2022). "Dysfunctional activation of the VWF/ADAMTS13 system in thrombotic microangiopathies (TMAs) (such as TTP, HUS, and DIC) results in microvessel occlusion by a complex web of VWF-rich thrombi causing tissue hypoperfusion and organ failure, potentially life-threatening." (PMID 28634421, 2017). "Patients with LN with thrombotic microangiopathy have stronger staining intensity and deposition of MBL, MASP1/3, CFB, CFD, C4d, and VWF." (PMID 41031884, 2025). "Severe ADAMTS13 deficiency leads to formation of the pathological lesion termed thrombotic microangiopathy (TMA) which affects renal function due to occluded glomerular capillaries containing VWF-rich microthrombi." (PMID 28139439, 2017). "TTP is a thrombotic microangiopathy (TMA) characterized by thrombopenia, mechanical hemolytic anemia, organ failure and VWF-rich microthrombi." (PMID 24238574, 2013). "Lastly, the release of IL-6 may at least in part account for the high levels of circulating VWF, but also in the decrease of ADAMTS13 activity, leading to a pro-aggregant phenotype and thrombotic microangiopathy-like features." (PMID 38915768, 2024). "The disturbance of the endothelial cells together with the release of large vWF multimers and the relatively inadequate cleavage of vWF due to a decreased ADAMTS13 can lead to increased interactions between the blood vessel walls and platelets, which then lead to thrombotic microangiopathy." (PMID 37092518, 2023). "TTP is a life-threatening thrombotic microangiopathy that arises when the metalloprotease ADAMTS13 does not cleave von Willebrand factor (vWF); this leads to the persistence of ultra-large vWF multimers that promote platelet aggregation and vessel occlusion." (PMID 28184292, 2017). "This functional interaction between fH, VWF and ADAMTS-13 could contribute to the pathogenesis of thrombotic microangiopathy in both TTP and aHUS and provide a mechanistic basis for the frequently observed clinical overlap between TTP and HUS." (PMID 23991205, 2013). "Moreover, oxidative stress may also induce accumulation of high molecular weight VWF multimers (UL-VWF), although at a minor extent than in thrombotic microangiopathies, where ADAMTS-13 is strongly reduced or absent so that proteolytic processing of UL-VWF multimers is severely defective." (PMID 23383177, 2013).
acquired von willebrand syndrome (67 papers, 2013 to 2025). "Such a loss of VWF high molecular weight multimers secondarily occurs in some cardiovascular diseases such as aortic stenosis (AS) and is designated as acquired von Willebrand syndrome (AVWS)." (PMID 38268521, 2024). "•Aortic stenosis can cause acquired von Willebrand syndrome via loss of von Willebrand factor (VWF) large multimers." (PMID 38268521, 2024). "Severe aortic stenosis (AS) causes acquired von Willebrand syndrome by the excessive shear stress–dependent cleavage of high molecular weight multimers of von Willebrand factor (VWF)." (PMID 38268521, 2024). "Acquired von Willebrand syndrome, linked to various conditions, is a hemostatic disorder due to reduced vWF activity." (PMID 38822325, 2024). "Acquired von Willebrand disease (aVWD) is the less common type of VWD due to an underlying medical disorder affecting von Willebrand Factor (VWF)." (PMID 36505449, 2022). "The increased degradation leading to a significant reduction or complete loss of HMW vWF multimers is typical for “acquired von Willebrand syndrome” (AVWS)." (PMID 35677828, 2022). "Acquired von Willebrand syndrome is characterized by a new onset bleeding tendency caused by a reduced concentration and/or function of von Willebrand factor." (PMID 34095769, 2021). "Another potential hypothesis is that acquired von Willebrand syndrome occurs due to loss of large molecular multimers of VWF due to increased shear stress and that bleeding in HHT can be reduced via von Willebrand factor replacement." (PMID 39336893, 2024). "First, the high shear forces and continuous flow of the Impella lead to the proteolysis of the high-molecular-weight von Willebrand factor, reducing platelet-binding affinity and causing acquired von Willebrand syndrome in a majority of patients within 24 h of initiating Impella use." (PMID 39041629, 2024). "Extreme thrombocytosis (platelets > 1000 × 109/L) has been associated with bleeding due to acquired von Willebrand syndrome (AVWS) as a result of absorption of VWF on platelets, although some postulate that increased cleavage might occur." (PMID 34741012, 2021). "However, pathologic vWF-ratios < 0.80 clinically associated with an acquired von Willebrand syndrome (AvWS) were only observed with BPX-80 from 300 min onwards." (PMID 34431015, 2021). "Acquired von Willebrand syndrome (aVWS) is a rare hematological disorder depicted by dysfunctional or deficient von Willebrand factor activity and can be associated with underlying hematological malignancies such as non-Hodgkins lymphoma (NHL)." (PMID 39697971, 2024). "Acquired von Willebrand syndrome (aVWS) can occur due to a variety of pathogenic mechanisms, the majority of which contribute to an elevated degradation or clearance of circulating von Willebrand factor." (PMID 39697971, 2024). "Almost all patients suffered from acquired von Willebrand syndrome (AvWS), which can contribute to bleeding tendencies due to loss of the high molecular weight multimers of von Willebrand factor (vWF)." (PMID 39309601, 2024). "Aortic stenosis (AS) can cause acquired von Willebrand syndrome (AVWS) and valve replacement has been shown to lead to von Willebrand factor (vWF) recovery." (PMID 35838799, 2022). "One of the potential causes of MCS-related bleeding is acquired von Willebrand syndrome (AVWS), which is caused by the loss of high-molecular-weight multimers of von Willebrand factor (vWF)." (PMID 35208560, 2022). "Acquired von Willebrand syndrome (AVWS) is caused by an acquired deficiency of von Willebrand factor (VWF), a multimeric protein required for primary hemostasis." (PMID 36547451, 2022). "Thus, in conditions of high shear stress, e.g., extracorporeal assist devices or aortic stenosis, a loss of HMW VWF multimers results in acquired von Willebrand syndrome (AVWS), which is comparable to VWD type 2A." (PMID 40103791, 2025).
acquired von willebrand syndrome (continued). "Contributing factors include acquired von Willebrand syndrome due to shear stress-induced proteolysis of von Willebrand factor (vWF), formation of arteriovenous malformations (AVMs), diminished arterial pulsatility, and chronic anticoagulation." (PMID 40964558, 2025). "In ECMO-induced acquired von Willebrand syndrome, large vWF multimers are cleaved into small multimers; however, vWF: Ag levels did not decrease." (PMID 38822325, 2024). "Rapid clearance of factor VIII and vWF, the good response to intravenous immunoglobulins, and the presence of monoclonal gammopathy of undetermined significance allowed the diagnosis of acquired von Willebrand syndrome." (PMID 39105017, 2024). "Shortly after LVAD implantation, nearly all patients develop the acquired von Willebrand syndrome (AVWS), indicated by the loss of large multimers of the vWF and reduced adhesive activity of blood platelets." (PMID 36982712, 2023). "Bleeding events are an additional concern and can relate to acquired von Willebrand syndrome due to preferential consumption of large von Willebrand factor (VWF) multimers in settings of excessive thrombocytosis with counts > 1000–1500 G/L." (PMID 35215273, 2022). "The increased shear stress of the pulmonary vasculature in PAH can lead to conformational changes of the VWF multimers, which can result in acquired von Willebrand syndrome and, therefore, in reduced VWF:Ac and vWF Ac/Ag ratio." (PMID 32992591, 2020). "For instance, a platelet count (PC) > 1000 × 109/L can induce an acquired von Willebrand syndrome (AVWS), caused by the proteolytic reduction of von Willebrand factor (VWF) multimers due to the passive adsorption to the platelet membrane." (PMID 32629973, 2020). "Monitoring vWF on plasma from patients with acquired von Willebrand syndrome was evaluated and showed less than 10% of the activity of the vWF cofactor of both ristocetin and vWF antigen." (PMID 33193314, 2020). "One proposed mechanism of GI bleeding is acquired von Willebrand syndrome due to the fragmentation of high molecular weight multimers of vWF." (PMID 29433532, 2018). "Thrombotic events exceed the hemorrhagic complications in MPN which occur mainly due to depletion of ultralarge von Willebrand factor (VWF) multimers by thrombocytosis leading to acquired von Willebrand syndrome (VWS) and altered platelet function." (PMID 28698883, 2017). "We would like to present a case of a patient with paradoxical low flow/low gradient (LF/LG) severe AS and HS in whom acquired von Willebrand syndrome was confirmed by semiautomatic vWF multimer analysis and who was successfully treated with transcatheter aortic valve implantation (TAVI)." (PMID 40388768, 2025). "vWF: von Willebrand factor; AvWS: acquired von Willebrand syndrome." (PMID 39219970, 2024). "Different CVDs, such as aortic stenosis, hypertrophic obstructive cardiomyopathy, or congenital structural diseases can generate high shear stress in the bloodstream, leading to the excessive cleavage of VWF multimers, known as acquired von Willebrand syndrome." (PMID 37375810, 2023). "For further clarification of an acquired von Willebrand syndrome (AVWS) an analyses of VWF:Ac/VWF:Ag ratio was made, showing us that AVWS was present in all patients, and median application of 19,000 units of factor VIII/von Willebrand factor concentrates was performed." (PMID 35407516, 2022). "The Acquired von Willebrand Syndrome (AVWS) is a rare acquired bleeding disorder in which von Willebrand factor (VWF) is synthesized normally but immune complexes form with nonspecific antibodies associated with the primary disease leading to enhanced clearance by the reticuloendothelial system." (PMID 25922770, 2015). "Acquired Von Willebrand syndrome (aVWS), which is a more common cause of bleeding among MPN patients, was unlikely, as VWF antigen level and bleeding time were normal." (PMID 40636934, 2025).
acquired von willebrand syndrome (continued). "The rationale for assessing VWF (antigen-Ag and ristocetin cofactor-RCo) is to exclude acquired von Willebrand Syndrome (AVWS), measuring level and ratio." (PMID 38337414, 2024). "Device‐related factors such as acquired von Willebrand disease, thought to be due to shearing of von Willebrand factor, and development of mucosal arteriovenous malformations add to the risk of mucosal bleeding and 1 can see how this bleeding risk could potentially be even higher." (PMID 38618289, 2024). "Ineffective vWF functioning, which results in bleeding, is defined as acquired von Willebrand syndrome (AVWS)." (PMID 39768556, 2024). "Acquired von Willebrand syndrome (AvWS) is one such disorder, in which a decrease in circulating levels of von Willebrand factor (vWF) exists due to either anti-vWF antibodies or disruption of vWF multimers secondary to proteolysis." (PMID 37038581, 2023). "Acquired von Willebrand syndrome (AVWS) is characterized by structural or functional defects in von Willebrand factor typically presenting with mucocutaneous bleeding as well as excessive bleeding after surgery or trauma." (PMID 37674997, 2022). "While enzymatic proteolysis counterregulates prothrombotic function of unfolded vWF strings, increased loss of HMW vWF multimers in AS leads to acquired von Willebrand syndrome (avWS)." (PMID 31359325, 2019). "However, the susceptibility of an already damaged endothelium to increased shear forces from LVAD devices could additionally result in decreased vWF secretion and thereby development of acquired von Willebrand syndrome." (PMID 26565707, 2015). "Acquired von Willebrand syndrome (AVWS) is a rare clinical condition characterised by prolonged bleeding time and decreased levels of factor VIII and von Willebrand factor, as in congenital von Willebrand disease (VWD)." (PMID 27841910, 2016). "In addition to impaired platelet function, patients receiving ECMO may develop acquired von Willebrand syndrome; shear stress during extracorporeal support is responsible for conformational modifications of von Willebrand factor that becomes exposed to metalloprotease-mediated cleavage." (PMID 23531278, 2013). "Confirmation of acquired von Willebrand syndrome (AVWS) with ristocetin cofactor assay or vWF multimer analysis was not done due to the patient’s financial constraints." (PMID 40926954, 2025). "There are 2 types of VWF abnormalities: von Willebrand disease type 2A and 2B, in which the production of HMW-VWF multimers is reduced or consumptively reduced, and acquired von Willebrand syndrome." (PMID 39247211, 2024). "VWF is mostly known due to its role in several severe diseases such as von Willebrand disease (VWD) and acquired von Willebrand syndrome (aVWS)." (PMID 33919627, 2021). "Among the most discussed factors is the acquired von Willebrand syndrome (AvWS) as a result of mechanical destruction and proteolysis of high-molecular-weight multimers (HMWM) of von Willebrand factor (vWF), induced by shear stress." (PMID 28234916, 2017). "Platelet dysfunction due to acquired von Willebrand syndrome (AvWS) is considered one of the reasons for bleeding tendency in patients with MPD with remarkable thrombocytosis, owing to the increased number of platelets binding to highly prothrombotic ultra-large vWF and their removal from plasma." (PMID 27443161, 2016).